IDH1 (isocitrate dehydrogenase (NADP(+)) 1)
Diseases named in the same sentence as IDH1 in open-access papers (continued):
Sharing a sentence is not in itself a finding about the gene and the disease.
tumor (continued). "Models based on radiomic analysis, using machine learning, can identify imaging features that correlate with the molecular status of a tumor, such as IDH1 mutation, MGMT promoter methylation, or EGFR amplification." (PMID 41465586, 2025). "The existing literature has investigated the link between IDH1/2 mutation status, tumor grade, and overall survival, but findings across the literature have been varied." (PMID 40364090, 2025). "Innovative approaches in early-phase trials, such as the IDH1 Vaccine Trial, RNA-LPAs, and mRNA-based vaccines, can potentially target specific tumor mutations and reprogram the tumor microenvironment." (PMID 40746549, 2025). "In summary, we leveraged steady-state kinetics, metabolic profiling, epigenomics, and transcriptomics to connect the biophysical features of tumor-driving IDH1 mutations to in vivo phenotypes in tumor models." (PMID 40188944, 2025). "GBM is marked by genetic alterations, including EGFR amplification, PDGFRA mutations and IDH1/2 mutations, which drive tumor development and contribute to treatment resistance." (PMID 39781344, 2025). "As patient-derived IDH1 R132Q-driven tumor cells were unavailable due to the rarity of this mutation, we generated isogenic cell lines stably overexpressing IDH1 WT, R132H, R132Q, or empty vector (EV)." (PMID 40188944, 2025). "Given the frequency of IDH1/2 mutation in CS and its role in early tumor development, IDH1/2 represents both a distinguishing biomarker and a potential therapeutic target." (PMID 40867318, 2025). "Molecular diagnosis via NGS confirmed IDH1 R132H (in 11 tumors), IDH1 R132G (1 tumor), IDH1 R132L (1 tumor), and IDH2 R172G (1 tumor) mutations." (PMID 41373636, 2025). "PGDx next-generation sequencing showed that the tumor was wild-type for IDH1/2 and histone mutations, and had a pathogenic TERT promoter mutation." (PMID 39666263, 2025). "This is likely due to the IDH1 mutation in patient 15 influencing the lipid signature displayed by this tumour." (PMID 39816516, 2025). "Our research has revealed an association between IDH1 mutations and methylation of antigen-presentation-related genes, leading to their decreased expression and the development of an immune-cold tumor immune microenvironment (TME) in CCA." (PMID 40227772, 2025). "Organoids were generated from the tumor samples of 52 patients, of which 66.7% harbored the IDH1 mutation and 75% were recurrent tumors." (PMID 41226697, 2025). "The brain biopsy showed white and gray matter with mildly hypercellular areas, and tumor DNA sequencing showed the presence of a canonical IDH1 mutation." (PMID 40597877, 2025). "Increased hypermethylation and hypomethylation are well-documented in R132H IDH1-mutated tumor models and tumor tissue, though the mechanisms and consequences of hypomethylation are not understood." (PMID 40188944, 2025). "The proposed mechanism of increased VTE risk is increased podoplanin expression on tumor cells in IDH1 wildtype tumors, leading to platelet activation." (PMID 39851266, 2025). "This research aims to provide more personalized treatment strategies for tumor patients carrying the IDH1-R132H mutation to reduce the occurrence of kidney injury." (PMID 39306640, 2025). "Identifying IDH1 mutations provides deeper insights into treatment sensitivity and tumor behavior, facilitating the selection of appropriate therapeutic strategies." (PMID 40299088, 2025).
tumor (continued). "Together, these studies highlight an important unresolved question: do different concentrations of D2HG resulting from different IDH1 mutations lead to changes in tumor phenotype or phenotype intensity?" (PMID 40188944, 2025). "Circulating tumor DNA (ctDNA) is DNA fragments released by tumor cells, which can show tumor-specific gene mutations (such as IDH1/2, FGFR2 fusion) and epigenetic modifications (such as abnormal methylation)." (PMID 40673275, 2025). "A 2022 publication on diffuse glioma tumor tissue metabolome identified distinct metabolites affected by tumor histology, IDH1 mutation status, or therapy." (PMID 39227460, 2024). "Then ddPCR was used to further validate the presence of differences in tumor purity, and we found that the allele fraction (IDH1-R132H) in this important region was higher than that in unimportant regions (60.04% for P06A vs. 12.13% for P06B)." (PMID 38951603, 2024). "TBR for tumor tissue classified as IDH1-wildtype was found to be significantly higher than for IDH1-mutated tumor tissue (p < 0.001)." (PMID 39061219, 2024). "Overall, a correlation analysis of the presence of IDH1 mutation in cfDNA with the histological grade of tumor was also performed." (PMID 38172718, 2024). "The IDH1/2 mutation rate in different histological tumor types provides us with important insights into the clinical utility of IDH1/2 diagnostic markers and pathways of malignant neoplasms." (PMID 38248076, 2024). "When paired with an R132H-specific LNA-SALP, successful allelic discrimination occurred, even in cases where the IDH1-R132H mutational status was limited to a subpopulation of the tumor." (PMID 38566776, 2024). "IDH1 inhibitors, such as Ivosidenib and Vorasidenib, by disrupting the aberrant metabolic pathways associated with IDH1 mutations, hold promise in impeding tumor growth." (PMID 38541003, 2024). "Overall, the enhanced fluorescence is associated with low expression of ferrochelatase, overexpression of ABCB6, low expression of ABCG2, the accumulation of heme synthesis-related metabolites caused by IDH1 mutations, and the tumor microenvironment." (PMID 39518115, 2024). "Univariate Cox analyses indicated that the GS risk score, neoplasm grade, IDH1 mutation status, and MGMT promoter methylation were all significantly prognostic factors." (PMID 38819225, 2024). "Mutations in human isocitrate dehydrogenase 1 (IDH1) drive tumor formation in a variety of cancers by replacing its conventional activity with a neomorphic activity that generates an oncometabolite." (PMID 38464189, 2024). "In all 3 data sets, the splicing pattern of the 200 events as well as the AS scores were significantly associated with updated 2021 WHO tumor grades, IDH1 mutation status, and the predefined molecular subtyping." (PMID 38662454, 2024). "Multivariate analysis further confirmed that tumor grade and the presence of an IDH1 mutation were independent prognostic factors." (PMID 38982076, 2024). "In the patient's cohort with recurrent GBM, one third of this patients cohort, which presented with smaller tumor volumes and IDH1 mutation, revealed radiologic tumor volume reduction after laser ablation." (PMID 39897706, 2024). "This analysis incorporated information regarding tumor grade, age, sex, 1p/19q co-deletion status, IDH1 mutation status, MGMT methylation status, and risk score." (PMID 39574472, 2024). "The GS model also outperformed established clinical prognostic factors, including neoplasm grade, IDH1 mutation status, and MGMT promoter methylation, as indicated by higher area-under-the-curve (AUC) values in ROC curves." (PMID 38819225, 2024).
tumor (continued). "Tumor tissue samples were also classified as IDH1-wildtype or IDH1-mutated (n = 19 and n = 22, respectively), ATRX-retained or ATRX-lost (n = 19 and n = 13, respectively), and low- or increased-cell-density (n = 21 and n = 17, respectively)." (PMID 39061219, 2024). "In this GBM dataset strongest associations with patient survival were seen with IDH1 R132 mutations compared to patients with tumours bearing wild type IDH1." (PMID 38304083, 2024). "A Chi-squared test was conducted to evaluate the potential association between tumor grade and the presence of IDH1 mutation in cfDNA." (PMID 38172718, 2024). "Ivosidenib demonstrated promising anti-tumor activity in patients with locally advanced or metastatic CCA carrying IDH1 mutation." (PMID 38730642, 2024). "IDH1 was the gene most frequently altered by missense mutations in our validation cohort (7/40, 21%), with 6/7 alterations in intrahepatic tumours." (PMID 38877653, 2024). "It has been shown that a lower degree of tumor malignancy and the presence of IDH1/2 mutations are independent factors of better prognosis, which is consistent with the results of other studies." (PMID 39684714, 2024). "IDH1 R132C/S/L/G/Q mutations have been reported in patients at lower frequencies and support distinct tumor D2HG levels." (PMID 38710674, 2024). "Other Indian studies also showed a greater IDH1 mutation prevalence reaching as high as 84% of Indian patients tested —assuming that all aggressive tumours are being given a confirmed diagnosis." (PMID 39767640, 2024). "As expected, tumor grade, IDH1 mutation, MGMT promoter methylation, and Ki-67 expression were significantly associated with OS and PFS." (PMID 39049072, 2024). "Being female (OR 1.75, 95% CI 1.22–2.51) and having an IDH1 mutation (OR 15.54, 95% CI 4.73–51.05) persisted after adjustment for age, sex, ethnicity, histology, tumour location and extent of resection." (PMID 39767640, 2024). "The proportion of tumours tested for IDH1 mutations and MGMT promoter methylation were high (97.9% and 92.3%, respectively)." (PMID 39767640, 2024). "Other genes such as APC, KRAS, VHL and IDH1 were highly enriched for mutations in only one or two tumor types." (PMID 38200255, 2024). "Improved prognosis has been linked to tumor molecular characteristics such as MGMTp-met and IDH1 mutation." (PMID 38893240, 2024). "A significant association between IDH1 mutation both in tissue and cfDNA, age, tumor grade and OS was demonstrated by univariate Cox regression analysis." (PMID 38172718, 2024). "Although IDH mutation appear to provide an oncogenic trigger of gliomagenesis, clinical data have shown a strong association between IDH1 mutations and less aggressive glioma phenotypes exhibiting slower tumor growth." (PMID 38445960, 2024). "For each patient, DNA was extracted and quantified from paraffin-embedded sections of tumor tissue, and the mutational status of IDH1 (codons 105 and 132) and IDH2 (codons 140 and 172) genes was assessed." (PMID 38170705, 2024). "Clonally expanded GS827 EP2 cells exhibited an increase in proliferation compared with the original IDH1-mutant GS827 cells, which seemingly contradicts the putative tumor-driving role of IDH1 mutations." (PMID 39605316, 2024). "RPLS scores were lower in tumours harbouring IDH1 or IDH2 mutations (all 3 cohorts with data available), as well as FGFR2 fusions (2/3 cohorts)." (PMID 37758326, 2024). "TET can also be inhibited by accumulation of metabolites due to IDH1 R132 and other gain-of-function mutations, also resulting in tumor hypermethylation." (PMID 39406235, 2024). "The method was validated on 96 chondroid tumor samples and showed its efficiency in IDH1/2 mutation analysis when compared with IHC and real-time PCR with DNA melting analysis using TaqMan probes followed by Sanger sequencing." (PMID 38248076, 2024). "IDH1 is highly mutated in LGG tumor samples (77%) in which almost half of the mutations are annotated as truncating mutations." (PMID 38241355, 2024).
tumor (continued). "All 96 tumor samples were screened for IDH1 mutations, but due to an insufficient amount of the material, only 79 were analyzed for IDH2 mutations." (PMID 38248076, 2024). "The prediction performance of the proposed signature is superior to classical clinicopathological parameters, such as IDH1 mutation status, tumor grade, or 1p19q staining combined with ablation." (PMID 37183261, 2023). "BAY1436032 has also been shown to potently inhibit 2-HG production by several IDH1 mutations in engineered or patient-derived tumor cell lines, with IC50 values in the low nanomolar range." (PMID 37049661, 2023). "More recent studies have shown that AG-120 (ivosidenib) treatment decreased intracellular levels of 2-HG and induced differentiation in models of IDH1-mutated tumours." (PMID 37296846, 2023). "Our research seeks to comprehend any correlations between this aspect of patient care and variables such as tumor and peritumoral brain edema volumes, tumor grades and IDH1 mutation status." (PMID 37508938, 2023). "Another challenge for detecting IDH1 mutations is that they are heterozygous at the cellular level and heterogeneous at the tumor level; thus, the mutation is present at relatively low copy number in clinical samples." (PMID 37733671, 2023). "Similar augmentation of pMHC-I and PNA binding was seen in IDH1-treated mouse cells responding to a distinct tumor-associated Survivin epitope." (PMID 37161052, 2023). "The rCET is the region with the highest tumor cell density, more active growth, and more pronounced heterogeneity, so the contribution of this region to the predictive efficacy of IDH1 gene mutation is greater than that of the other two regions." (PMID 37354775, 2023). "Second, both H3K27M-vac and IDH1-vac target clonal driver mutations in proteins that are expressed in all cells of primary and recurrent tumors and are functionally relevant for tumor growth." (PMID 37735561, 2023). "Texture analysis of MRI data can accurately predict IDH1 mutation, 1p/19q co-deletion, histological grading, and tumor progression." (PMID 37360350, 2023). "This indicates that IDH1 mutation allows cells to invade the nearby parenchyma in the initial stages of tumour development." (PMID 37296846, 2023). "To conclusively label tumor cells within high density cultures, we exploited the IDH1 mutation which is typically shared in > 95 % of tumor cells as it occurs early during tumorigenesis." (PMID 36632958, 2023). "Only patients with a connotated age and a confirmed WHO grade 2 or 3 tumor with IDH1 (n = 358; 51%) or IDH2 (n = 19; 2.6%) mutations were included (n = 377)." (PMID 36648586, 2023). "Tumor stage, radiation therapy status, IDH1 mutation status, and chr1p19q co-deletion status, these elements all have been identified as important factors related to patients’ overall survival." (PMID 37955724, 2023). "The risk scores were in agreement with previous clustering analyses and provided good discriminatory functions in terms of tumor molecular characteristics, such as fewer IDH1 mutations, 1p19q co-deletion, and MGMT methylation in the high-risk group." (PMID 37403043, 2023). "In terms of molecular tumor profile, 4 patients (33.3%) had IDH1-mutated tumors and methylation of MGMT gene promoter was observed in 6 patients (50.0%)." (PMID 37245011, 2023). "To address the impact of IDH1 mutation on anti-tumor T cell activity, we examined how IDH1 and IDH1R132H transfection impacted GL26 progression in DC vaccine-treated syngeneic (C57BL/6; B6) hosts." (PMID 37161052, 2023). "In 2016, the WHO Classification of Tumours of the Central Nervous System (revised 4th edition) incorporated isocitrate dehydrogenase 1 and 2 (IDH1/2) mutation status into the classification of diffuse gliomas." (PMID 37504251, 2023). "Seven patients had a tumor with the typical R132H mutation, whereas non-R132H mutations (R132C n = 2, R132S n = 1) were found in the three other patients with IDH1-mutated tumors." (PMID 37685329, 2023).
tumor (continued). "In vaccinated GBM with increased CD8 tumor signal post-treatment (i.e., local treatment response), IDH1 DNA or RNA loss predicted significantly shorter patient survival." (PMID 37161052, 2023). "Tumor-associated IDH1 and IDH2 mutations occur almost exclusively at different arginine residues in the active enzyme site." (PMID 37563735, 2023). "Univariate Cox regression showed that tumor stage, radiation therapy status, IDH1 mutation status, and chr1p19q co-deletion status had an impact on overall survival." (PMID 37955724, 2023). "IDH1 mutation caused downregulation of leukocyte chemotaxis, resulting in reduced infiltration of immune cells and suppression of the tumor-associated immune system." (PMID 37543576, 2023). "From the histopathology results of the muscle gastrocnemius, IDH1-mutation in the tumor resulted in a smaller cross-sectional area in the muscle gastrocnemius compared to the control groups and non-mutated CT26 tumor-bearing cancer cachexia mice." (PMID 37741882, 2023). "We collected TISF1 samples 16 months after surgery and confirmed one mutation (IDH1:p.R132H) with a VAF of 3.7% associated with local tumor progression." (PMID 37533228, 2023). "Tumor-derived IDH1 mutation sensitizes cells to ferroptosis, and inhibition of mutant IDH1 produces the oncometabolite D-2-hydroxyglutarate (D-2-HG), which confers resistance to erastin-induced ferroptosis." (PMID 37580393, 2023). "The oncometabolite 2-HG has been shown to promote histone methylation, and IDH1 mutations are associated with tumor hypermethylation phenotype in gliomas." (PMID 36611031, 2023). "IDH1 mutation in CT26 tumor-bearing mice resulted in increased expression of Ube2d1, Trim63, and Fbxo32, while ivosidenib treatment inhibited the upregulation of UPP-related enzymes." (PMID 37741882, 2023). "With the emerging focus on the mechanisms of tumor molecular markers such as IDH1 mutation and MGMT methylation status, new treatment targets and better evidence to guide clinical decision making is a hopeful future." (PMID 37071297, 2023). "We evaluated the effect of ivosidenib on alleviating IDH1 mutation-exacerbated cancer cachexia in CT26 tumor-bearing mice." (PMID 37741882, 2023). "We investigated the association between age, tumour site, extent of resection, Ki67 index, IDH1 mutation, MGMT promoter methylation and baseline performance status with subsequent tumour relapse." (PMID 37715122, 2023). "To further explore the effect of IDH1 mutation on viral replication in vivo, we performed tissue virus titration in a bilaterally tumor model." (PMID 37880243, 2023). "Pharmacological inhibitors of mutant IDH1 with validated safety profiles are currently used in the clinic to treat patients with tumours harbouring IDH1 mutations." (PMID 37086156, 2023). "The gain of the function of IDH1 mutation in the CT26 tumor also resulted in high circulating D2HG levels and upregulated E3 ligases in skeletal muscle." (PMID 37741882, 2023). "In tumours with mutated IDH1/2, it has been observed that the tumour cells dependence on mitochondrial metabolism for energy is enhanced by multiple folds." (PMID 37692182, 2023). "Next-generation sequencing (NGS) was used for the study of isocitrate dehydrogenase 1 (IDH1) mutations in the primary tumor." (PMID 35740557, 2022). "A nomogram model was developed to predict the overall survival (OS), which included age, tumor grade, IDH-1 mutations, and inflammation-nutrition score." (PMID 35495765, 2022). "For IDH1 mutations, the most predictive features are as follows: well-defined tumor borders, central areas of cysts with low T1 and FLAIR suppression, and minimal or absent enhancement." (PMID 36290819, 2022). "It has been reported that r-2-hydroxyglutarate (r-2HG) is a tumour metabolite produced by the mutation of isocitrate dehydrogenase 1/2 (IDH1/2), which can increase the level of FTO m6A and inhibit tumour growth and has antitumor effects." (PMID 35688823, 2022).